GSDME (gasdermin E)
Diseases named in the same sentence as GSDME in open-access papers (continued):
Sharing a sentence is not in itself a finding about the gene and the disease.
breast carcinoma (continued). "The DNA methyltransferase inhibitor decitabine (DAC) could increase the expression of GSDME by demethylation in mouse breast cancer and colon carcinoma cells." (PMID 33634141, 2021). "Although expression levels of GSDME and GSDMB were positively correlated with clinical benefit in several kinds of cancers, increased GSDMB expression was associated with poor clinical outcome in breast cancer." (PMID 33406603, 2021). "Similarly, GSDME, which is also highly expressed in normal tissue, is downregulated by promoter DNA methylation in colorectal cancer and breast cancer." (PMID 34590363, 2021). "Furthermore, to understand the roles of GSDME in breast cancers, we analyzed the expression of GSDME according to different breast cancer subtypes using public datasets (CCLE dataset; GSE100878; GSE2034)." (PMID 33558527, 2021). "Taken together, these results showed that pyroptosis mediated by GSDME in breast cancer cells could be rescued by reducing the protein level of active Caspase‐3, Caspase‐8 or direct inhibition of GSDME." (PMID 34369076, 2021). "However, due to DNA methylation, GSDME was only highly expressed in certain cancer tissues such as kidney cancer, lung cancer, breast cancer, neuroblastoma, skin melanoma, and esophageal cancer." (PMID 34778452, 2021). "For example, the caspase-3/GSDME axis could activate pyroptosis through the ROS/JNK pathway in breast cancer." (PMID 34731088, 2021). "Mechanistically, GSDME may mediate paclitaxel and doxorubicin-induced pyroptosis in breast cancer cells through the caspase-9/caspase-3 pathway, activate anti-tumor immunity, and promote the efficacy of paclitaxel and anthracycline-based neoadjuvant chemotherapy." (PMID 38954046, 2024). "They discovered that A-C/NP treatment could trigger GSDME-mediated pyroptosis by disrupting mitochondrial homeostasis and ROS accumulation, resulting in immunogenic cell death and exhibiting potent cytotoxicity in breast cancer cells." (PMID 38104141, 2023). "Hence, GSDME methylation has emerged as a valuable prognostic indicator for breast cancer." (PMID 38066523, 2023). "Indeed, some studies have proposed that GSDME is often silenced by methylation in breast cancer." (PMID 38066523, 2023). "However, 5-aza-dC could trigger GSDME expression at the transcription level in breast cancer cells, and a quantitative DNA methylation assay further proved the promoter hypermethylation of GSDME." (PMID 36823153, 2023). "In breast cancer (BC), GSDME exerts a certain effect on doxorubicin-mediated pyroptosis, regulating caspase-3-mediated ROS level increases and stimulating JNK phosphorylation-based activation." (PMID 36867378, 2023). "Moreover, the GSDME-mediated pyroptosis was also induced by 4f in breast cancer cells." (PMID 35551332, 2022). "Moreover, GSDME (DFNA5) can be cleaved by granzyme B (GzmB) to activate pyroptosis and stimulate tumor-associated macrophages, tumor-infiltrating natural-killer and CD8+ T lymphocytes to evoke anti-tumor immunity in breast cancer." (PMID 36090993, 2022). "In addition, GSDME expression is suppressed in various cancers and its low level is correlated with poor survival of breast cancer patients, indicating GSDME may serve as a tumor suppressor." (PMID 36090993, 2022). "Similarly, GSDME expression in patient-derived breast cancer cells correlates with increased survival of patients because of pyroptosis triggered by granzyme B released by cytotoxic T cells; accordingly, its absence is associated with reduced lifespan and a high risk of metastasis." (PMID 35844522, 2022). "Thus, we hypothesized that GSDME expression elevation is a possible route for CDK7 inhibition to suppress breast cancer cell survival." (PMID 34490348, 2021).
breast carcinoma (continued). "Additionally, it showed that the DOX‐induced cardiotoxicity and pyroptosis in breast cancer cells can be minimized by reducing the protein level of GSDME; thus, these outcomes provide a new research target and implications for the anticancer investigations and therapeutic applications." (PMID 34369076, 2021). "Instead, this activation triggers a switch toward pro-death signalling by inhibiting HK2, thereby initiating GSDME-dependent pyroptosis in EMT6 and 4T1 murine breast cancer cells." (PMID 41415273, 2025). "In breast cancer treatment, Dihydroartemisinin induces pyroptosis in breast cancer cells by promoting the AIM2/caspase-3/DFNA5 (gasdermin E) axis." (PMID 36341437, 2022). "Moreover, triclabendazole administration significantly promoted formation of cleaved caspase-3, cleaved PARP, and GSDME-NT, indicating that triclabendazole induced apoptosis-to-pyroptosis, which was consistent with the in vitro studies showing the effects of triclabendazole on breast cancer cells." (PMID 34305590, 2021). "In this study, we used breast cancer MCF-7 and MDA-MB-231 cell lines as a cellular model, which have been shown to express GSDME protein, to explore the effects of triclabendazole on cancer by inducing GSDME-dependent pyroptosis via activating caspase-3." (PMID 34305590, 2021). "We found that the protein expression of cleaved GSDME (GSDME‐N) was higher in both MDA‐MB‐231 and T47D breast cancer cell lines under DOX treatment, which is approximately consistent with the morphological results." (PMID 34369076, 2021). "In this study, high expression of GSDME protein was detected in breast cancer MDA-MB-231 and MCF-7 cells, but not in T47D and EMT-6 cells." (PMID 38954046, 2024). "Our results demonstrated that 4f induces G2 phase arrest of cell cycle, cell apoptosis and GSDME-mediated pyroptosis in breast cancer cells without significant toxicity to human normal mammary epithelial cell." (PMID 35551332, 2022). "In vivo, anti-tumor immunity could be stimulated through GSDME activation 20, suggesting an advanced anti-tumor potential of GSDMD and GSDME in breast cancer." (PMID 35541900, 2022). "TaqMan-methylation specific PCR was used to analyze the methylation of GSDME in tissues of breast cancer patients and non-cancer patients." (PMID 35462927, 2022). "In breast cancer, TP63 induced the expression of GSDME via binding a specific site in GSDME." (PMID 36389801, 2022). "We discovered that the protein level of GSDME was lower in breast cancer cells MB231, HS578T, MCF-7, and ZR-75-1 than in non-tumorigenic human mammary epithelial MCF10A cells." (PMID 34490348, 2021). "Although expression of GSDME is lower in all types of breast cancer than that in other types of cancer cells, we found that GSDME expression in TNBC was significantly higher than that in non‐TNBC, supporting a previous report." (PMID 33342034, 2021). "The ZR-75-1 cell line is a type of breast cancer cell with lower GSDME expression than MCF-7 cells and lacking caspase-3 expression." (PMID 34490348, 2021).
breast carcinoma (continued). "However, whether FBZ—a structurally related benzimidazole—exerts anti-breast cancer effects through GSDM-dependent pyroptosis, particularly via the caspase-3/GSDME axis, remains undefined." (PMID 40756987, 2025). "In GSDME-null cancer cell lines, such as human lung adenocarcinoma PC-9 cells and human breast cancer MDA-MB-468 cells, raptinal could not induce pyroptosis." (PMID 37460805, 2023). "Notably, there is a negative correlation between GSDME expression and estrogen receptor levels in breast cancer, leading to its designation as inversely correlated with estrogen receptor expression (ICERE-1)." (PMID 38066523, 2023). "However, no studies have investigated the relationship between GSDME expression and chemotherapy resistance in breast cancer." (PMID 36867605, 2023). "The level of GSDME expression varies by the type of breast cancer which manifest it could be a novel premonitory marker in breast cancer while GSDMD expression is not clear fully." (PMID 36119049, 2022). "In addition, considering that GSDME was overexpressed in TNBC cells compared with luminal subtype cells, which are non-aggressive breast cancer cells, tetraarsenic hexoxide-induced pyroptosis may be dependent on the GSDME expression level in breast cancer cells." (PMID 33558527, 2021).
lung carcinoma (62 papers, 2018 to 2025). "As it did in lung cancer, simvastatin caused pyroptotic cell death in gastric cancer by upregulating the expression of caspase 3 and GSDME." (PMID 37752941, 2023). "In lung cancer cells, loss of GSDME expression promotes resistance to chemotherapy, while overexpression of GSDME enhances the sensitivity of cells to chemotherapy drugs." (PMID 35957895, 2022). "high levels of GSDME expression in cancer tissues of patients with lung cancer was associated with a higher survival rate after surgery." (PMID 34553845, 2022). "GSDME expression levels were found to be higher in the cell membranes of some lung cancer tissues, which is consistent with the possibility that GSDME causes cell disintegration and death by forming holes in the cell membrane." (PMID 34553845, 2022). "Specifically targeting KRAS, EGFR, or ALK mutants by small-molecule inhibitors elicit GSDME-mediated pyroptotic cell death in oncogenic mutations-driven lung cancer, pinpointing a previously unrecognized role of GSDME-dependent pyroptosis in molecular targeted therapy." (PMID 33941231, 2021). "In lung cancer, paclitaxel and cisplatin-induced pyroptosis by a caspase-3/GSDME mechanism, interestingly, we found significantly increased expression of GSDME, which might act as a risk factor." (PMID 34910689, 2021). "Elevated GSDME expression is associated with a higher postoperative survival rate and a lower lymph node metastasis rate, which suggests that it may serve as a predictor of prognosis in lung cancer patients." (PMID 37752941, 2023). "The discovery of the immunological regulatory effects of GSDME on lung cancer provides a new potential target to enhance lung cancer immunotherapies." (PMID 40721578, 2025). "Recent studies have made considerable progress in understanding the role of GSDME-mediated pyroptosis in lung cancer growth, the lung cancer microenvironment, and the effect of GSDME methylation on lung cancer treatment." (PMID 39147707, 2024). "Particularly, the role of gasdermin E (GSDME) in the process of pyroptosis reveals its tremendous potential in lung cancer therapy." (PMID 39147707, 2024). "Both cisplatin and PTX can induce caspase‐3/gasdermin E (GSDME)‐dependent pyroptosis in the lung cancer cell line A549 to varying degrees." (PMID 39224538, 2024). "Studies on the lung cancer cell line A549 have revealed that both cisplatin and paclitaxel induce pyroptosis via the caspase-3/GSDME signaling pathway, with cisplatin exhibiting a more pronounced effect than paclitaxel." (PMID 38304430, 2024). "GSDME was originally identified as DFNA5, a deafness gene and now seems to have many penetrated aspects of lung cancer." (PMID 38225586, 2024). "GSDME expression is reduced, whereas overexpression increases chemosensitivity in lung cancer tissue." (PMID 37752941, 2023). "For instance, one study reported that under the condition of GSDME overexpression, the proliferation of hepatocellular carcinoma cells was inhibited, and another study shared similar findings in the case of lung cancer." (PMID 37681881, 2023). "DC, have been shown to induce caspase-3/GSDME-mediated pyroptosis and are beneficial for the prevention and treatment of cervical and lung cancers, respectively." (PMID 38016064, 2023). "Paclitaxel, a representative chemotherapeutic agent for lung cancer, induced pyroptosis in lung cancer cells by activating caspase-3 and GSDME." (PMID 38283351, 2023). "When GSDME expression is high, cisplatin and paclitaxel activate the caspase-3/GSDME pathway, convert normal chemotherapy-induced apoptosis into pyroptosis and inhibit lung cancer cell growth." (PMID 38104141, 2023). "Cisplatin can trigger caspase‐3 and GSDME‐dependent pyroptosis in A549 cells, indicating cisplatin has a good potential in lung cancer therapy with high expression of GSDME." (PMID 37125240, 2023).
lung carcinoma (continued). "A recent study have reported that GSDME is ubiquitously expressed in lung cancer and that the expression of GSDME in OSCC (oral squamous cell carcinoma) is significantly higher than that in normal mucosa." (PMID 37085908, 2023). "The GSDMD family, especially GSDMC, GSDMD, and GSDME can be consider as potential markers for the diagnosis and prognosis of lung cancer patients, including NSCLC." (PMID 36523974, 2022). "Another PRG, GSDME, is expressed in multiple molecular subtypes of lung cancer, the depletion of which reduces GSDME-dependent pyrolysis in non-small-cell lung cancer cells." (PMID 35255915, 2022). "Inversely, high GSDME expression is corresponding to a better prognosis in lung cancer and oral cancer." (PMID 35462927, 2022). "In the present study, we used immunohistochemical staining to analyze the relationship between GSDME expression level and the prognosis of patients with lung cancer." (PMID 34553845, 2022). "Our study found that the expression level of GSDME in lung cancer tissues was higher than in the normal tissues adjacent to cancer tissues." (PMID 34553845, 2022). "Chemotherapy agents such 5-FU, paclitaxel and cisplatin were shown to induce GSDME-mediated pyroptosis in a caspase-3-dependent manner in gastric cancer and lung cancer, which is considered as a switch between apoptosis and pyroptosis." (PMID 36605187, 2022). "When trapped in liposomes, these complexes can trigger mitochondria-mediated apoptosis and GSDME-mediated pyroptosis in a variety of cancers, including lung carcinoma, gastric adenocarcinoma, and melanoma." (PMID 36209102, 2022). "In this study, we found that myricetin induces pyroptosis in lung cancer cells through endoplasmic reticulum stress that leads to the activation of caspase-3 and the cleavage of GSDME." (PMID 36091790, 2022). "For example, studies have found that the chemotherapy drug cisplatin induces pyroptosis in A549 lung cancer cells via caspase 3/GSDME activation." (PMID 35712653, 2022). "The expression of GSDME is significantly reduced in lung cancer tissue compared with normal tissue; in addition, patients with a low expression of GSDME presented a poor prognosis under cisplatin treatment." (PMID 36142404, 2022). "In this study, we analyzed GSDMD and GSDME protein expression levels after treatment of lung cancer cells with myricetin." (PMID 36091790, 2022). "In lung cancer cells, Doxorubicin was also reported to capably induce robust pyroptosis and GSDME cleavage." (PMID 36071875, 2022). "We examined the protein levels of GSDME, caspase‐3, caspase‐8, and caspase‐9 in lung tissue samples from 100 patients with lung cancer by using immunohistochemistry." (PMID 34553845, 2022). "Meanwhile, it is reported that the increased level of GSDME activated by caspase-3 with chemotherapeutic drugs such as cisplatin and paclitaxel leads to the switch from apoptosis to pyroptosis in lung cancer cells." (PMID 35819638, 2022). "Analysis of the results of crystal violet staining in vitro found that GSDME deletion alleviated drug response and generated more drug-resistant persistence in lung cancer cells." (PMID 35462927, 2022). "As anticipated, elevated GSDME protein was detected at a time-dependent manner in lung cancer cells, such as NCI-H1975, HCC827, and NCI-H1437." (PMID 34901025, 2021). "Accordingly, knockdown of GSDME remarkably suppressed cisplatin-induced pyroptosis in lung cancer cells." (PMID 33634141, 2021). "In lung cancer, genetic deletion of GSDME promoted drug resistance, while GSDME over-expression led to enhanced drug sensitivity in vivo and in vitro." (PMID 34305590, 2021). "The chemotherapeutic agent cisplatin triggered pyroptotic cell death in lung cancer cells by activating the caspase-3/GSDME pathway." (PMID 33634141, 2021). "Although cisplatin is widely believed to kill tumors by causing apoptosis, recent evidence suggests cisplatin induces lung cancer A549 cell through caspase-3/GSDME pathway." (PMID 33941231, 2021).